KLRG1 (killer cell lectin like receptor G1)
Diseases named in the same sentence as KLRG1 in open-access papers (continued):
Sharing a sentence is not in itself a finding about the gene and the disease.
tumor (continued). "In a separate context, the study also identified heterogeneity in the expression of KLRG1 and found that the specific abundance of PD1+KLRG1− cells within that subset positively correlated with optimal induction of tumor antigen-specific T cells and overall treatment outcome." (PMID 37735591, 2023). "To test if blocking KLRG1 engagement with this neutralizing antibody has any effect on the anti-tumor activity of T cells in the MMTV-PyMT model, we treated 12-week WT MMTV-PyMT mice with either isotype control or anti-KLRG1 antibody once every 3 days for three weeks." (PMID 36703228, 2023). "Remarkably, the identified pre-exhausted KLRG1+EOMES+CD28+ cluster was well represented also in periphery, sharing a phenotypical and functional signature with tumor infiltrating T cells, thus likely providing a feasible tool for the identification of responsive patients." (PMID 37898752, 2023). "Moreover, the proliferation marker Ki-67 was abundantly expressed by tumor-infiltrating CD8+ T cells expressing CD431B11, KLRG1, and NKG2A, whereas PDOX therapy only significantly increased KLRG1/Ki-67 double-positive cells." (PMID 36796366, 2023). "In the tumor-draining lymph node (tdLN) and bone marrow, significantly higher frequencies of CD431B11+CD4+ T cells but not CD431B11+CD8+ T cells in the PDOX treated mice were detected, and these cells differentially expressed ICOS, CD38, CD39, and KLRG1." (PMID 36796366, 2023). "Importantly, these CD8+ T cells displayed a more prominent activation state but less exhausted phenotype by decreased expression of KLRG1 and LAG3, presumably induced by a greater recognition of TAAs in the tumor niche." (PMID 38235131, 2023). "We also observed that responders had increased percentages of splenic KLRG1+ mature NK cells and tumor-infiltrating CD11b-/CD27- immature NK cells, and decreased percentages of tumor-infiltrating CD11b+/CD27-activated NK cells two weeks after treatment initiation." (PMID 37446056, 2023). "Klrg1+ iNKT cells, expressing the NKT1-like cytokine IFN-γ and cytotoxic molecules (FasL and granzyme A/B), persisted for several months in the lung and maintained long-term anti-tumor function." (PMID 37903859, 2023). "CB-specific T cells primed in wild-type mice and transferred into tumor-bearing Batf3–/– mice did not acquire Foxp3 or the Klrg1+Lag3+ subset." (PMID 35393950, 2022). "Notably, cDC1s are also key drivers of the differentiation of Klrg1+IFN-γ+ T cells, which our prior studies show are particularly critical for tumor control." (PMID 35393950, 2022). "Some NK cells with aging showed a reduced ability to eliminate tumor cells or damaged cells, which is attributed to the expression of the inhibitory receptor KLRG1, particularly in CD56+ dim NK cells, and both NKG2A and KLRG1." (PMID 36291665, 2022). "Administration of anti-KLRG1 antibody does not modify primary tumor growth but has been shown to reduce lung metastases in breast cancer mouse models." (PMID 35164813, 2022). "Using KLRG1 as an mRNA vaccine can achieve anti-tumor immunity by activating the immune system without altering KLRG1 expression in cancer cells themselves to affect the cell cycle." (PMID 35265614, 2022). "Then, we investigated the expression of KLRG1 and CBFA2T3 in different tumor stages." (PMID 35265614, 2022). "Phenotypically, the spleen and tumor-derived donors expressed similar levels of Bcl-2, TIM3, CXCR3, PD-1, and had undergone similar patterns for memory vs effector differentiation as determined by CD62L, CD127, and KLRG-1." (PMID 34867942, 2021). "Remarkably, CD8+ T cells from B16F10E-KO were more enriched with KLRG1+ effectors and activated CD69+ cells, and less enriched with CD103+ cells than B16F10E, which correlated with a decreased production of active TGF-β by the former tumours." (PMID 34471106, 2021).
tumor (continued). "Altogether, these results revealed that KLRG1, BTK and CCR2 may interact through cell surface receptor signaling pathway to influence the proliferation of tumor cells or affect the immune response indirectly." (PMID 34187403, 2021). "GL261 tumors showed the lowest frequency of KLRG1+ cells and CD25+ cells of the CD4 subset, whereas 70–80% of CD8 T cells in CT2A were positive for Lag3 and Tim3, markers of dysfunctional T cells in comparison to the other tumor types analyzed." (PMID 32764562, 2020). "KLRG1+CD8 T cells also expressed high amounts of chemokine and chemokine receptors, which is consistent with their higher migration capacity into tumor sites." (PMID 31664180, 2019). "Together, our study showed that alloDC-immunization could induce potent antitumor effect through the expansion of KLRG1+CD8 T cells, which can work as both preventive and therapeutic tumor vaccines." (PMID 31664180, 2019). "Statistic data also showed that compared with KLRG1−CD8 T cells, which did not display obvious cytotoxicity against tumor cells, KLRG1+CD8 T cells killed B16 cells and EL4 cells with much higher killing rates." (PMID 31664180, 2019). "This indicated that these KLRG1+CD8 T cells might also be activated CD8 T cells with a higher frequency for tumor reactive T cells, which could inhibit tumor growth efficiently." (PMID 31664180, 2019). "A variety of inhibitory and stimulatory receptors could co-express on tumor antigen-specific CD8+ T cells (including CD160, KLRG-1, TIM-3, 2B4, BTLA, and LAG3)." (PMID 31708918, 2019). "Statistical data also presented that both the proportions and numbers of tumor infiltrating KLRG1+CD8 T cells was increased in DBA DC, but not B6 DC-vaccinated mice." (PMID 31664180, 2019). "Our data have shown that more KLRG1+CD8 T cells could migrate and infiltrate into tumor sites than KLRG1−CD8 T cells." (PMID 31664180, 2019). "Further, on day 10 of combination treatment, the number of activated (CD8+ CD69+) T cells in the tumor were increased and T-cell functions were enhanced, with an up-regulated expression of the effector T-cell markers, IFN-γ, Granzyme B, and KLRG1." (PMID 31781498, 2019). "Notably, HPK1 KD mice showed markedly increased pro-inflammatory pathways in response to priming with tumor antigens as shown by the enhanced related gene expression, e.g. S100A8, GZMB, NKp44, CXCL14, CX3CL1, CD1d2, KLRG1, CD11c, NLRP3 and MUC1." (PMID 30913212, 2019). "Our studies suggest that small molecule agonists of GPR18 might augment the size of the KLRG1+ effector CD8 T cell compartment, an effect that might be beneficial, for example, during viral responses or in the context of tumor immunotherapy." (PMID 29670628, 2018). "Comparing tumour infiltrating ILC populations with circulating ILC, showed that ILC populations have an activated phenotype in tumour tissue with higher expression of MHC-II, KLRG1, CD69 and CD44." (PMID 29587679, 2018). "Our results revealed that targeting KLRG1 significantly reduced protection as mice depleted with KLRG1 mAb showed faster tumor growth than the combination treated without KLRG1 mAb." (PMID 28388572, 2017). "Unlike the tumor infiltrating effector T-cells, KLRG1 expression on Tregs was not significantly elevated in combination treated mice relative to those receiving FVAX alone." (PMID 21559358, 2011). "Overall, our ability to initiate autologous tumor killing by blocking KLRG1’s interactions with E-cadherin nominate KLRG1 not just as a marker of cytotoxic CD4+ T cells with shared tumor specificity, but as an additional regulatory step (separate from PD-1) that can further mobilize killing." (PMID 40299576, 2025). "However, adding anti–E-cadherin increased tumor cell death, which was specifically seen with KLRG1+ cells but not KLRG1–cells (top)." (PMID 40299576, 2025). "However (and unexpectedly), challenging mice with tumor cells did not affect the SP CD11b+ NK cells or the SP CD11b+ KLRG1+ expression levels." (PMID 38553761, 2024).
tumor (continued). "The addition of PD-1 blockade to NAC promoted anti-tumor immunity through T and B cells recruitment in the tumor microenvironment and induced tumor-infiltrating CD8+ T cells skewed toward CD127+ and KLRG1+ phenotypes, which may be assisted by CD4+ T cells and B cells." (PMID 37231145, 2023). "The study showed that this recombinant OV suppressed the antiviral cytotoxicity of KLRG1+ NK cells by approximately 50%, thus providing sufficient time for OV-CDH1 to complete viral replication, initiate secondary infection, and increase the tumor-killing potency." (PMID 37040283, 2023). "While NK cells were able to control tumor growth and metastasis, ILC1s and intILC1s upregulated tumor progression and resistance-related pathways with a higher expression of inhibitory receptors (NKG2A, KLRG1) and the production of PDGF-AB, a pro-angiogenic molecule." (PMID 35281021, 2022). "When looking closely at the phenotype, they identified a subset of ILC2s, enriched in the tumor tissue but absent in the non-tumoral area, lacking the expression of killer cell lectin-like receptor subfamily G member 1 (KLRG1), a known marker for mature and activated ILC2s." (PMID 35281021, 2022). "Additionally, we saw that KLRG1 had drastically reduced cytotoxicity, often only killing between 0 and 20% of K562 tumor cells, compared to the CD3ζ-only CAR, which killed approximately 75% of tumor cells at each timepoint." (PMID 36350984, 2022). "Tumor-infiltrating CD8+ T cells also showed decreased abundance of TOX, programmed cell death protein-1 (PD-1), T cell immunoglobulin, mucin domain-3 (TIM-3), and killer cell lectin-like receptor subfamily G member 1 (KLRG1), indicating the cells remained functional effector cells." (PMID 33353953, 2020). "However, considering the lack of study on KLRG1 signaling, how the KLRG1+CD8 T cells recognize the tumor cells and how the cytotoxicity of these cells is regulated, needs to be further studied." (PMID 31664180, 2019). "Thus, in comparison with WT KLRG1+ NK cells, KLRG1+ NK cells from Ackr2−/− mice increase tumor killing through enhanced CCR2 responsiveness and resulting recruitment in closer proximity to CCL2-expressing tumor deposits." (PMID 30158126, 2018). "Reduction of KLRG1+CD8+ T cells in tumor-bearing mice significantly attenuated the tumor clearance effects of Vax/aGITR/aPD-1 therapy and allowed the tumors to grow larger compared to the non-treated KLRG1 mAb therapeutic group." (PMID 28388572, 2017). "In this regard, it is noteworthy that 4-1BB co-stimulation increased CD28 expression and critical effector molecules needed for tumor killing (Perforin, GB, Eomes) without significantly increasing KLRG-1, a marker for end-stage effector cells approaching senescence." (PMID 23560068, 2013). "Therefore, we believed that the development of KLRG1 as an mRNA vaccine could help to stimulate KLRG1+Effector CD8+T Cells to differentiate into memory T cells of other lineages and produce effective anti-tumor immunity." (PMID 35265614, 2022). "A similar pattern has been reported in non-small cell lung cancer (NSCLC) CD8+ tumor infiltrating lymphocytes (TILS), where PD-1-high cells are earlier stage CD27+ T cells, while KLRG1+ cells are later-stage CD27– T cells that are not PD-1-high." (PMID 39832302, 2025). "Single cell RNAseq analysis of tumor infiltrating CD8 T cells shows positive correlation of CTLA-4, TIM-3, LAG-3, TIGIT, GITR, 4-1BB, and OX40 with PD-1 but negative correlation of KLRG1 with PD-1." (PMID 39832302, 2025). "In fact, KLRG1 expression on CD3+ T cells was already elevated in the blood and spleen of age-matched aging humanized mice in the absence of tumor." (PMID 37752597, 2023). "Herein we report that CD4+ and CD8+ T cells co-expressing KLRG-1 and CD57 were present in peripheral blood, tumor, and invaded and non-invaded lymph nodes from patients with untreated BC." (PMID 34386013, 2021).
tumor (continued). "By contrast, surface markers of exhaustion (PD-1), activation (KLRG1, Granzyme B, perforin, Interferon gamma (IFNγ)) and death (CD95) were no different on tumor infiltrating CD8+ T cells between TM and vehicle treated mice." (PMID 32085796, 2020). "Instead, a population of KLRG1 expressing CD8 T cells increased, whose potent cytotoxicity against multiple tumor cells suggested that this tumor killing was not TCR-dependent and antigen specific." (PMID 31664180, 2019). "However, although we found enrichment of KLRG1 on circulating tumor-TCR-matching cytotoxic CD4+ T cells, the functional relevance of this ligand-receptor interaction for tumor recognition and killing in this subset has not been studied." (PMID 40299576, 2025). "Moreover, the upregulation of KLRG1, an inhibitory receptor on NK cells that binds to non-MHC class I ligand cell-junction proteins, also plays a crucial role in tumor surveillance." (PMID 39660132, 2024). "This is in contrast to tumor, where a much higher proportion of both cytotoxic and noncytotoxic CD4+ T cells globally expressed PD-1 and Tim-3 (which may be related to exhaustion), but lower levels of KLRG1, suggesting distinct mechanisms of regulation from blood." (PMID 40299576, 2025).
infection (164 papers, 2010 to 2026). The state of being infected such as from the introduction of a foreign agent such as serum, vaccine, antigenic substance or organism. "Tnfrsf25 showed the biggest fold change among downregulated genes in the RORα-deficient KLRG1+ effector T cells isolated at days 7 and 10 after primary infection." (PMID 40895530, 2025). "Here we have shown that loss of Ifng-as1 is specific for KLRG1+ terminally mature NK cells induced by infection." (PMID 37828009, 2023). "In lungs, however, prior IAV infection elicited effector CD8+ T cells with highly activated CD38 and/or CD25 phenotypes, while SFV-only infection elicited distinct effector CD8+ T cells with increased frequencies of KLRG1 expression, a hallmark of short-lived effector T cells." (PMID 39817772, 2025). "Since very few SMAD4-deficient CTLs expressed KLRG1 during infection with LM-OVA, we investigated whether these cells were located in the vasculature or peripheral tissues." (PMID 35942952, 2022). "Indeed, although markers such as PD-1 are strongly associated to LCMV clone 13 infection, KLRG1, CX3CR1, and NKG2A expression is mostly connected to MCMV, and Ly6Chi and CD127hi expression is connected to LCMV Armstrong." (PMID 33458613, 2021). "Also, a TEM cell cluster expressing high levels of Ly6C and CD127 (Li cluster 1) associated to LCMV Armstrong was detected in the liver, whereas liver KLRG1+CX3CR1+NKG2A+ TEM cells (Li cluster 8) associated predominantly to MCMV-GP33 infection." (PMID 33458613, 2021). "Thus, inflationary T cells comprise a population of T cells that can protect peripheral tissues from pathogenic infections and their efficacy can be regulated by balancing the number of KLRG1- CMV-specific cells during priming." (PMID 31083700, 2019). "Thus, KLRG1 is associated with iILC2-mediated protection from infection." (PMID 37696896, 2023). "We demonstrate that KLRG1 restricts CD4+ T cells to the lung vasculature early during infection, and limits lesion homing at chronic stages." (PMID 41643900, 2026). "In‐depth analysis revealed that the expression of CD38+PD‐1+ was higher, while KLRG1+ expression was lower on KbE1159+CD8+ T cells in SFV + IAV–infected brain in comparison to SFV‐only infection." (PMID 39971320, 2025). "The SLP-76HA mutation slightly enhanced the number of CD127−KLRG1+ short-lived effector cells (SLEC) but had little effect on those of CD127+KLRG1− memory-precursor effector cells (MPEC) at 7 days post-infection." (PMID 41000640, 2025). "Effector CD4+ T cells in the brains of the SFV‐only and SFV + IAV–coinfected groups displayed similar activation phenotype of CD38+ PD1+, KLRG1+ compared with IAV‐only infection." (PMID 39971320, 2025). "At day 14 postinfection, ~60% of m59 tetramer+ and m139 tetramer+ CD8+ T cells expressed KLRG1, and this expression was restored to near naïve levels following long-term infection." (PMID 41417899, 2025). "KLRG1 expression is upregulated during infection with several parasitic protozoans, including Toxoplasma gondii, Nippostrongylus brasiliensis, and Leishmania." (PMID 38898461, 2024). "Collectively, KLRG1 is detected in a considerable number of memory and effector T cell subsets, even during infection, and it is more prevalent in subsets from CHB patients with a greater capacity to suppress the virus." (PMID 38776335, 2024). "In summary, KLRG1 expression is increased on immune cells after repeated and sustained antigenic stimulation and can serve as a marker for assessing the extent of infection in patients infected with HCV and Mtb." (PMID 38898461, 2024). "Regarding the classical cell-surface inhibitory receptors PD-1 and Lag-3, we certainly observed parallel expression with KLRG1, as has been reported in some infections and cancers." (PMID 38776335, 2024).